LDHD (lactate dehydrogenase D)
Description:
The mitochondrial D-lactate dehydrogenase is a stereoselective dehydrogenase that targets a wide variety of D-2-hydroxyacids, particularly those with small to moderately sized hydrophobic groups attached to the C2 atom. It includes D-lactate which is generated in small amounts either endogenously through the methylglyoxal metabolism pathway or exogenously via intestinal bacterial activity and dietary intake. The dehydrogenase acts specifically on D-lactate, not on its stereoisomer L-lactate, and prevents the toxic accumulation of D-lactate in the organism. By converting branched-chain D-2-hydroxyacids into branched-chain ketoacids, it may indirectly regulate branched-chain amino acid metabolism (By similarity).
Synonyms: DLACD
Tractability: PROTAC: its protein half-life has been measured.
Gene: Protein-coding gene on chromosome 16 (75,111,855 to 75,116,782, reverse strand). Ensembl gene ENSG00000166816.
Subcellular location: Mitochondrion
Subcellular location (Human Protein Atlas): Cytosol; Mitochondria
Pathways (Reactome):
Metabolism of proteins: Mitochondrial protein degradation
Protein localization: Mitochondrial protein import
Gene Ontology:
Molecular function: (2R)-2-hydroxycarboxylate dehydrogenase activity; D-lactate dehydrogenase (FAD) activity; lactate dehydrogenase activity; protein binding; catalytic activity; FAD binding; flavin adenine dinucleotide binding
Biological process: lactate catabolic process
Cellular component: mitochondrion; mitochondrial inner membrane
Genetic constraint (gnomAD): Loss-of-function variants: 56 observed, 53.29 expected, observed/expected ratio (o/e) 1.05, 90% interval 0.85 to 1.31. The synonymous counts are far from expectation, so gnomAD's model fits this gene poorly and the ratio says little. Missense variants: 746 observed, 665.84 expected, observed/expected ratio (o/e) 1.12, 90% interval 1.05 to 1.19. Synonymous variants: 350 observed, 286.23 expected, observed/expected ratio (o/e) 1.22, 90% interval 1.12 to 1.34.
Homologues: Orthologues: chimpanzee LDHD (99% identical), macaque LDHD (97% identical), dog LDHD (88% identical), mouse Ldhd (85% identical), rabbit LDHD (84% identical), guinea pig LDHD (83% identical), rat Ldhd (77% identical), tropical clawed frog ldhd (71% identical), zebrafish ldhd (65% identical), pig LDHD (64% identical), Caenorhabditis elegans F32D8.12 (50% identical), Caenorhabditis elegans F32D8.4 (10% identical). Paralogues in human: D2HGDH (29% identical), AGPS (24% identical).
Diseases named in the same sentence as LDHD in open-access papers:
LDHD is named in the same sentence as 37 diseases in open-access papers, as found by Europe PMC text mining. Sharing a sentence is not in itself a finding about the gene and the disease. The quoted sentences say what the papers report.
glioma (6 papers, 2021 to 2025). A benign or malignant brain and spinal cord tumor that arises from glial cells (astrocytes, oligodendrocytes, ependymal cells). "Importantly, previous studies reported that AIFM3, LDHD, LYNX1, SCN2B or TMEM56 were all negatively corelated with glioma, and GINS1, KIFC1, NUF2, NUSAP1 or TPX2 were both positively related to glioma progression." (PMID 33277782, 2021).
uterine sarcoma (4 papers, 2020 to 2025). "In uterine sarcoma, the expression of LDHD is far higher than that in patients with uterine myoma or cellular leiomyoma, suggesting the possibility of LDHD for aiding in the pathological diagnosis of tumor types." (PMID 36612084, 2022).
prostate carcinoma (3 papers, 2021 to 2023). A carcinoma that arises from epithelial cells of the prostate gland. "Lidia de Bari believed that the expression of LDHD is higher in prostate cancer cells than in normal tissues." (PMID 36171887, 2022). "Besides, elevated LDHD expression is found in prostate cancer cells, which exhibit higher mitochondrial D-lactate metabolism than normal cells." (PMID 37863926, 2023).
clear cell renal cell carcinoma (2 papers, 2022). "In clear cell renal cell carcinoma, low expression of LDHD is a promising predictor of poor prognosis; however, its role in CRC has not been previously reported." (PMID 36091047, 2022). "A previous study showed that the downregulation of LDHD expression could be a predictor of poor prognosis in patients with clear cell renal cell carcinoma." (PMID 36158120, 2022).
Obesity (2 papers, 2021 to 2024). Accumulation of substantial excess body fat. "In contrast, LDHD was found decreased in VAT and SKM from individuals with obesity." (PMID 38703299, 2024).
renal carcinoma (2 papers, 2021). A carcinoma arising from the epithelium of the renal parenchyma or the renal pelvis. "The high expression of FBP1, ALDOB, LDHD, and SUCLA2 indicated a longer DFS and a low risk of developing renal cancer." (PMID 33564363, 2021). "Findings suggest that decreased LDHD expression may be a predictor of poor prognosis in patients with renal failure and even renal cancer." (PMID 34027419, 2021).
breast carcinoma (1 paper, 2022). "The results illuminated that arm-level deletion and arm-level gain of LDHD were associated with breast cancer immune cell infiltration." (PMID 36171887, 2022).
cholangiocarcinoma (1 paper, 2023). A carcinoma that arises from the intrahepatic biliary tree (intrahepatic cholangiocarcinoma) or from the junction, or adjacent to the junction, of the right and left hepatic ducts (hilar cholangiocarcinoma). "In addition to D-lactic acidosis, down-regulation of LDHD expression is related to poor prognosis of many tumors such as cholangiocarcinoma and renal cell carcinoma." (PMID 37863926, 2023).
colorectal cancer (1 paper, 2021). A primary or metastatic malignant neoplasm that affects the colon or rectum. "Furthermore, LDHD is downregulated in colorectal cancer, and is also a hot spot for somatic mutations in colorectal cancer." (PMID 33707455, 2021).
gout (1 paper, 2025). A condition characterized by painful swelling of the joints, which is caused by deposition of urate crystals. "The clinical findings observed in patients with LDHD deficiency occur in a broad phenotypic spectrum, with some patients having only increased plasma urate/gout and others presenting with neurological findings and early‐onset psycho‐motor developmental delay." (PMID 40678184, 2025). "Take‐home message: Human D‐lactate dehydrogenase deficiency can be caused by pathogenic variants of the LDHD gene, and shows a broad phenotypic variability, with some patients only having increased plasma urate/gout and others neurological findings and psycho‐motor developmental delay." (PMID 40678184, 2025).
lactic acidosis (1 paper, 2023). Metabolic acidosis characterized by the accumulation of lactate in the body. "Here the authors report the structure of LDHD bound with various ligands and show that LDHD is a general dehydrogenase for D-2-hydroxyacids with small to moderate-size hydrophobic moieties and investigate loss-of-function mutations that play an important role in D-lactic acidosis." (PMID 37863926, 2023).
osteoarthritis (1 paper, 2018). A noninflammatory degenerative joint disease occurring chiefly in older persons, characterized by degeneration of the articular cartilage, hypertrophy of bone at the margins and changes in the synovial membrane. "VDR polymorphisms, Fok I and Taq I also have been studied in other common bone disorders like osteoporosis and osteoarthritis in addition to LDH and LDHD." (PMID 30356314, 2018).
renal cell carcinoma (1 paper, 2022). "In a cohort study of renal cell carcinoma, the LDHD expression in the tumor is reported to be influenced by the tumor’s pathological T stage, and the down-regulated LDHD is associated with poor overall survival." (PMID 36612084, 2022).
short bowel syndrome (1 paper, 2023). "These substrates can serve as potential biomarkers of LDHD deficiency, providing differential diagnostic criteria for D-lactic acidosis patients with LDHD mutations or with short bowel syndrome." (PMID 37863926, 2023). "However, other diseases such as short bowel syndrome may also lead to accumulation of D-lactate, which can be confused with that caused by LDHD mutations." (PMID 37863926, 2023).
thyroid cancer (1 paper, 2024). "LDHD expression was low in lung, kidney and thyroid cancer tissues." (PMID 38291366, 2024).
cancer (14 papers, 2019 to 2025). A tumor composed of atypical neoplastic, often pleomorphic cells that invade other tissues. "Low expression of HAGH (GLO2) as well as of LDHD was also prominently connected with poorer 5-year overall survival across different cancers (TCGA PANCAN dataset; N = 11,506 patients)." (PMID 40461450, 2025). "Analyzing the expression of LDHs genes including LDHA, LDHB, LDHC and LDHD in all cancer types, we found that the expression of LDHA, LDHB and LDHD was higher than that of LDHC in pan-cancer." (PMID 38291366, 2024). "In vitro experiments revealed that LDHD can affect HCC proliferation, migration, and invasion by regulating MMPs expression and EMT via Akt signaling pathway, which provides a new perspective on the anti-cancer molecular mechanism of LDHD in HCC." (PMID 38291366, 2024). "Analysis of the differential expression of LDHs subtype across cancer patients revealed that LDHD expression was low in HCC patients." (PMID 38291366, 2024). "We further analyzed the expression of LDHs genes in 33 cancer types and found that LDHD expression was significantly lower in pan-cancer, especially in CHOL and COAD." (PMID 38291366, 2024). "Upon analyzing the expression, clinical practice and immune infiltration of LDHs subtype in various cancers, it was discovered that LDHD plays a key role in the prognosis and immune infiltration of HCC patients." (PMID 38291366, 2024). "As D-lactate is considered to be released from carcinoma cells and its role in cancer has been gradually uncovered, combined with the detection of D-lactate and LDHD in blood and/or tissues, it will be a potential predictive marker of diagnosis of cancers." (PMID 36612084, 2022). "Except for LDHA and LDHB, LDHC and LDHD are expressed in various cancers." (PMID 37547725, 2023). "Except for LDHA and LDHB, LDHD also has been described in some cancers." (PMID 36612084, 2022). "A future study applying αHB may be an alternative choice for anticancer drug therapy and an optional inhibitor for revealing the characteristics and biological functions of LDHD in different types of cancer." (PMID 36612084, 2022). "Role of LDHC and LDHD has not been fully explored in cancers; a recent loss-of-function study in LDHD identified two different homozygous variants of LDHD resulting in enzymatic loss-of-function and increased concentrations of D-lactate." (PMID 31146503, 2019). "Higher expression of GAPDH correlates to worse ten-year survival across all cancer types, while the opposite is the case for HAGH (GLO2) and LDHD (PANCAN dataset)." (PMID 40461450, 2025). "This, in turn, stimulates the production of D-lactate dehydrogenase (LDHD) protein and promotes cancer stem cell-like features in ESCC." (PMID 40693409, 2025). "LDHD was identified to play an important role in the prognosis of HCC patients, according to a comprehensive analysis of LDHs in pan-cancer." (PMID 38291366, 2024). "In this pathway, conversion of D-lactate to pyruvate and further to oxaloacetate is increased in cancer cells by upregulation of HAGH, LDHD, and PC." (PMID 36282866, 2022). "Recent findings have shown that in cancer cells, 13C-labeled D-lactate, a substrate for LDHD, is not converted by cells for pyruvate or citrate." (PMID 39169201, 2024). "Among them are genes involved in cell adhesion/migration processes (PEPD), migratory potential of cancer cells (ACTN1), ECM (LTBP2, PRG4, ADGRL1, CD9), or in metabolic processes (LDHD, ALDH7A1), as well as proto-oncogenes or their ligands/inhibitors (FYN, PPP1R13L)." (PMID 30838002, 2019).
tumor (9 papers, 2019 to 2025). "The results showed that LDHD gene expression was significantly associated with age, gender, race, T stage, histological grade, pathological stage, tumor status and AFP." (PMID 38291366, 2024). "The promoter methylation level of LDHD was significantly higher in the 4 tumor groups than in the normal group." (PMID 38291366, 2024). "LDHD has been reported to be a regulator of energy metabolism and is involved with tumor cell glycolysis within the tumor microenvironment." (PMID 33834191, 2021). "In all cases, however, tumor adjacent tissue demonstrated higher mRNA transcript levels of both GLO enzymes as well as LDHD compared to healthy lungs, indicating that the cells in the tumor microenvironment might have to cope with higher MG levels than usual." (PMID 40461450, 2025). "We observed that LDHD could promote tumor cell growth, migration, self-renewal, and tumorigenic potential in ESCC." (PMID 37582812, 2023). "Given the investigations of LDHD are limited, the function of LDHD in the regulation of tumor initiation and progression remains unclear." (PMID 37582812, 2023). "We explored the expression levels of four major lactate dehydrogenase (LDHA, LDHB, LDHC, and LDHD) and found that LDHA was significantly higher expressed in tumor tissue-derived cells and LDHB was higher expressed in normal tissue-derived cells." (PMID 37795453, 2023). "To probe the expression of LDHD in ESCC patients, we performed immunohistochemistry and found that LDHD had a higher enrichment in ESCC tumor tissues than in paired adjacent tissues." (PMID 37582812, 2023). "Moreover, LDHD is enriched significantly in ESCC-CSCs rather than differentiated tumor cells and high LDHD status is connected with poor prognosis in ESCC patients." (PMID 37582812, 2023). "Of note, LDHD, the most downstream enzyme of the GLO pathway, was detected only in very few samples of our cohort in both tumor and healthy tissue, with no striking change in abundance." (PMID 40461450, 2025).
LDHD also shares sentences with these, for which no sentence is quoted: esophageal squamous cell carcinoma (3 papers); atrophic gastritis (1); bone disorder (1); chronic fatigue syndrome (1); diabetes (1); endometriosis (1); fibroids (1); gastric tumors (1); hepatocellular carcinoma (1); infection (1); Insulin resistance (1); kidney disease (1); liver disease (1); lung carcinoma (1); motor developmental delay (1); osteoporosis (1); osteosarcoma (1); renal failure (1); Type 2 Diabetes (1); ‐lactate dehydrogenase deficiency (1).